IL6 (interleukin 6)
Diseases named in the same sentence as IL6 in open-access papers (continued):
Sharing a sentence is not in itself a finding about the gene and the disease.
cancer (continued). "Bidirectional communication between cancer stem cells (CSCs) and cancer-associated fibroblasts (CAFs) amplifies stemness via paracrine stimulation of the IL-6/STAT3, TGF-β/SMAD, and CXCL12/CXCR4 signaling pathways." (PMID 41439922, 2025). "Constitutive activation of STAT3 (pSTAT3), a hallmark of many cancers, is driven by persistent exposure to cytokines such as IL-6, IL-10, and oncostatin M, leading to continuous phosphorylation and nuclear translocation of STAT3." (PMID 41463071, 2025). "Interleukin 6 (IL-6) is a pleiotropic proinflammatory cytokine and acts as a main mediator of both local and systemic cancer-associated inflammatory responses." (PMID 40255422, 2025). "The elevated levels of IL-6 are often associated with inflammation and diseases, including autoimmune disorders, certain cancers, and infectious diseases." (PMID 40291032, 2025). "These chemokines were uniquely selected in view of their importance in lymphocyte recruitment, their role in host response against cancer, and the contribution of IL‐6 and IL‐8 as prototypic senescence‐associated secretory phenotype (SASP) components." (PMID 39420514, 2025). "Studies demonstrate that mast cell-derived cytokines (including TGF-β and IL-6) critically promote MSCs differentiation into cancer-associated fibroblasts." (PMID 40598621, 2025). "Cancer-associated adipocytes (CAAs), inflammation in adipose tissue, increased IL-6 (interleukin-6) and TNF (tumor necrosis factor) levels, and changes in adiponectin levels are known mechanisms." (PMID 41002580, 2025). "Pooled analysis revealed that IL-6 promoters rs1800795 and rs1800796 were significantly correlated with an augmented risk of cancer in Asia and Caucasian." (PMID 39980561, 2025). "Paraneoplastic inflammatory syndrome (PIS) with fever and biological inflammation is a rare but severe condition often caused by the systemic production of interleukin 6 (IL-6) by cancer cells." (PMID 39754984, 2025). "Among healthy individuals, elevated CRP and other inflammatory cytokines Interleukin-1 (IL1) and IL6 are associated with increased risks of cardiovascular disease, cancer, and infections." (PMID 40475250, 2025). "In PDAC, in the early stages of cancer, interleukin-6 (IL-6) secreted by SCs was linked to analgesia since activated SCs exhibited a transcriptomic profile with anti-inflammatory and anti-nociceptive features." (PMID 40806192, 2025). "IL-6, which has previously been linked to muscle wasting in cancer patients, was also upregulated, but at a lower level than CXCL5." (PMID 41392310, 2025). "Chronically elevated plasma IL-6 levels in cancer patients were associated with blunted diurnal variations in HPA activity." (PMID 41210498, 2025). "Key mechanisms include cytokine involvement [e.g., interleukin-6 (IL-6)], phenotypic alterations in macrophages and natural killer (NK) cells, and the plasticity of cancer-associated fibroblasts (CAFs)." (PMID 40177538, 2025). "Another report demonstrates that cancer-associated fibroblast-derived IL-6 increased c-Met expression in MET-unamplified GC cells through the IL-6/IL-6R/JAK2/STAT3 signalling pathway." (PMID 37950040, 2024). "IL-6 is a pro-inflammatory cytokine implicated in various aspects of cancer development, including proliferation, survival, and angiogenesis." (PMID 38756274, 2024). "Despite the promising results of preclinical and clinical studies, the use of anti-IL-6 pathway therapy in the treatment of PC faces several challenges, one of which is the heterogeneity of primary cancer types commonly associated with PC." (PMID 38689325, 2024). "This contributes to chronic systemic inflammation with enhanced concentrations of circulating cytokines such as CRP and IL-6 and adipokines, which is associated with cancer progression and poor survival in patients with CC." (PMID 38172335, 2024).
cancer (continued). "Inflammatory cues associated with cancer, such as IL6, IL4, IL13, and TNF, promote the generation and expansion of heterogeneous immature myeloid-derived cells, comprising polymorphonuclear/granulocytic (PMN/G-MDSCs) and monocytic (M-MDSCs) subsets." (PMID 38785789, 2024). "In turn, cancer-associated fibroblasts secrete matrix proteins that sustain tumor cell proliferation and chemokines (IL-6, CLC5, CXCL14, CXCL12) that promote epithelial-mesenchymal transition and OC cell dissemination." (PMID 38165032, 2024). "Fibroblasts were extracted from OSCC tissues and normal oral mucosa to confirm the expression of IL-6 and subsequently classified as cancer-associated fibroblasts (CAFs) and normal fibroblasts (NFs), respectively." (PMID 38510850, 2024). "IL-6 is an inflammatory cytokine that exerts a broad effect on the systemic immune system and is associated with various diseases, including cancer." (PMID 39139287, 2024). "IL6 has been implicated in asbestos-induced MM, and IL6 release due to chronic inflammation in other cancers is known to promote the expression of CD39, the rate-limiting ecto-enzyme of the ATP-adenosine pathway." (PMID 38592450, 2024). "This has significant implications in the realm of therapeutic applications and scientific research, especially concerning IL-6 associated diseases, such as cancer." (PMID 38801471, 2024). "The upregulation of SHC1 activated immune-associated and cancer-related pathways, such as epithelial-mesenchymal transition, interferon-gamma response, inflammatory response, and the IL6/JAK/STAT3 pathway." (PMID 38763954, 2024). "Li and his colleagues also have indicated F. nucleatum isolated from the mouth affects cancer cells in oral squamous cell cancer, causing them to produce IL6 and IL8." (PMID 39030445, 2024). "STAT3, a downstream IL6 effector, is activated in most cancers, including OC, and has been linked to aggressive OC clinical behavior." (PMID 39766086, 2024). "High serum IL-6 levels are associated with worse tolerance to chemotherapy in some types of cancer, as well as a poor prognosis in patients with HNSCC." (PMID 38540309, 2024). "The IL-6 signaling pathway is implicated in the onset and progression of various diseases, including cancer, autoimmune disorders, and inflammatory diseases." (PMID 38256942, 2024). "Nevertheless, the mechanism behind IL-6-induced cancer-associated fibroblast activation needs further investigation." (PMID 37588204, 2024). "Elevated levels of proinflammatory cytokines, such as osteopontin and interleukin-6, have been associated with poor outcomes in cancer." (PMID 38589844, 2024). "Chronic inflammation, associated with autoimmune disorders, cancer, and other chronic inflammatory diseases, is caused by IL-6." (PMID 37971510, 2024). "Dysbiosis of the endometrial microbiota and pro-inflammatory cytokines such as IL-6, IL-8, and IL-17 are implicated in infertility and in cancer." (PMID 38337827, 2024). "Clinical conditions in CRC patients with high expression levels of those cytokines and/or pro-inflammatory cytokines such as IL-6 and IL-8 have been associated with drug resistance, distant metastasis, cancer recurrence, and a poor 5-year survival rate." (PMID 39056778, 2024). "In the context of IR, IL-6 has been implicated in cancer progression and resistance to treatment by reducing oxidative stress and DNA damage." (PMID 39498386, 2024). "Recently, active STING signaling has been linked to the survival of chromosomally unstable cancers in an IL-6 dependent manner involving both NF-κB and signal transducer and activator of transcription 3 (STAT3) activation." (PMID 38660307, 2024). "Cancer-associated fibroblasts (CAF) derived IL6 induced the differentiation of CD73+γδTreg in normal breast tissue through IL6/STAT3 pathway." (PMID 39188712, 2024). "The inclusion of IL-6 in our diagnostic index enhances its predictive accuracy and underscores the importance of inflammatory processes in cancer prognosis." (PMID 39697224, 2024).
cancer (continued). "The interleukin 6 (IL-6) signaling pathway is crucial in mediating inflammation and has been implicated in cancer progression, metastasis, and drug resistance." (PMID 38999963, 2024). "All myokines identified in our study as potentially associated with cancer cachexia are normally released by various cells, predominantly within the immune system (IL-6, IL−8, FABP3) and adipose tissue (leptin, FSTL-1)." (PMID 39411315, 2024). "The ability of cancer-associated fibroblasts to secrete IL-6 has also been mechanistically linked to the emergence of chemoresistant disease in individuals with NSCLC." (PMID 38440120, 2024). "We measured IL-6, TNFα, and IL-1β, which are risk factors for cancer development and are also involved in HIV-1 pathogenesis." (PMID 38166062, 2024). "In a recent meta-analysis of 24 studies with 6,936 ICI-treated cancer patients, IL-2 levels were significantly associated with longer OS, and inversely, IL-6 and IL-8 levels were with shorter OS." (PMID 38799450, 2024). "Interleukin 6 (IL-6), an inflammatory cytokine, plays an important role in the stimulation of acute phase responses; however, dysregulation of IL-6 is associated with cancer progression and resistance." (PMID 38493133, 2024). "The IL-6/JAK/STAT3 pathway is aberrantly hyperactivated in many types of cancers and is generally associated with a poor clinical prognosis." (PMID 39247610, 2024). "Targeting IL-6 and its downstream signaling pathways in combination regimens has shown promise in preclinical and clinical studies for various types of cancer that commonly cause PC." (PMID 38689325, 2024). "Among the various pro-inflammatory cytokines implicated in cancer development, Interleukin-6 (IL6) has gained significant attention due to its multifaceted role in tumorigenesis." (PMID 39766086, 2024). "Western blotting was performed to assess the proteins that are associated with proliferation (Survivin, IL-6) and cancer stem cell function (Oct4, Sox2) in cell lysates prepared from control and etoposide treated groups." (PMID 38957610, 2024). "Early plasma cytokine increases in IL-6 levels were also associated with both cancer-specific and all-cause mortality." (PMID 39403935, 2024). "For instance, IL-6 induces associated cancer cell proliferation, apoptosis inhibition, angiogenesis and enhanced drug resistance." (PMID 38529301, 2024). "In several cancers, including hepatocellular carcinoma, renal cell carcinoma, colorectal cancer, and glioblastoma, increased levels of circulating IL-6 have been linked to a poor response to therapies that target the VEGF/VEGFR pathway." (PMID 39759107, 2024). "High IL-6 levels have been closely associated with cancer progression and poor prognosis for patients." (PMID 38529301, 2024). "For instance, cancer-associated fibroblast (CAF) produces IL6 within OC-TME, aids in the remolding of the extracellular matrix, and induces epithelial-mesenchymal transition (EMT)." (PMID 39766086, 2024). "Inflammatory cytokines, such as TNF-α and IL-6, are elevated in HF and have been implicated in promoting cancer cell proliferation and survival." (PMID 39346905, 2024). "So, some CAFs secrete some growth factors such as FGF, IL-6, and IL-8, which cause the growth and expansion of cancer cells and the polarization of immune cells towards exhausted cells." (PMID 39030445, 2024). "High IL-6 levels have been shown to be associated with a poorer prognosis in cancer, HNSCC included." (PMID 38672565, 2024). "Among all 32 cytokines quantified, only early on-treatment fold changes of IL-6 was significantly associated with increased risk of grade ≥ 2 irAEs and both cancer-specific and all-cause mortality after multitesting adjustment." (PMID 39403935, 2024).
cancer (continued). "IL-6 has been associated with the epithelial-to-mesenchymal transition (EMT) process in cancer cells as well." (PMID 38338683, 2024). "IL-1β and IL-6, in particular, are associated with cancer, promoting cancer initiation and progression." (PMID 39340596, 2024). "Changes were completely reversible after IL-6 was deleted from the injected cancer cells, pointing towards a causative role of IL-6 in the installation of neoplastic cachectic syndrome at least in this mice model." (PMID 39683624, 2024). "Increased inflammatory cytokines in cancer cachexia, such as interleukin (IL)-1β, IL-6, and Tumor Necrosis Factor-α (TNF-α), cause lipid degradation and reduced lipid synthesis." (PMID 39272951, 2024). "We also demonstrated that IL‐6 secreted from macrophages stimulates the growth of HCC cells, which is consistent with a report that IL‐6 is associated with poor prognosis, recurrence and metastasis in various types of cancer." (PMID 37974543, 2024). "This metabolite was previously correlated with elevated blood interleukin-6 in older adults, which was associated with an increased risk of cancer and mortality." (PMID 38433226, 2024). "Elevated IL-6 levels are linked to the radiation response in prostate cancer, glioblastoma, liver cancer, and lung cancer, highlighting its significant role in cancer therapy." (PMID 39498386, 2024). "The IL-6 serum concentration is found to be associated with poor prognosis of many types of cancer, particularly in later stages." (PMID 39518029, 2024). "Signal transducer and activator of transcription 1 (STAT1) is a cancer associated gene, which is involved in the cytokines (interferon-α/γ and interleukin-6) and growth factor response." (PMID 38227591, 2024). "IL‐6, a proinflammatory cytokine strongly linked to weight loss, is increasingly recognized as a critical factor in the development of cancer cachexia." (PMID 39523982, 2024). "Overall, IL-6 is associated with cancer development and progression by suppressing T cell activity against tumors and inhibition of dendritic cell maturation, among other mechanism." (PMID 39411143, 2024). "The blood level of IL-6 correlates with the amount of weight loss in cancer patients, and an elevated IL-6 level shows a positive correlation with reduced patient survival." (PMID 38474057, 2024). "The incorporation of IL-6 into the diagnostic index highlights the importance of inflammatory processes in cancer prognosis." (PMID 39697224, 2024). "Below, we have summarized pre-clinical studies and clinical trials examining IL-6 pathway blockade in cancers that are commonly associated with PC." (PMID 38689325, 2024). "Here we tested the causal role of IL-6 in cancer cachexia by knocking out the IL-6 gene in C26 cells." (PMID 38671295, 2024). "M1 ATMs release TNF-α and IL-6, which not only contribute to insulin resistance but are also associated with cancer recurrence." (PMID 39064705, 2024). "In some contexts, IL-17 has been associated with promoting cancer progression by stimulating the production of pro-inflammatory cytokines and chemokines, such as IL-6, IL-8, and CXCL1, which contribute to inflammation and tumor growth." (PMID 38792785, 2024). "Another study showed that IL-6 is more strongly associated with all-cause mortality and cancer-related mortality, whereas CRP only primarily predicts cardiovascular mortality over a 16-year follow-up period." (PMID 39589972, 2024). "Escalation of circulating IL-6 levels has been previously reported to associate with systemic inflammation in cancer patients undergoing surgery 52, thus facilitating EMT and BCSCs expansion 33 and contributing to progressive metastasis." (PMID 38505617, 2024). "Inflammation is closely related to cancer development and progression, and inflammation is primarily associated with changes in the levels of IL-6, TNF-α, and IFN-γ." (PMID 39508039, 2024).
cancer (continued). "employed a co‐culture methodology to ascertain that cancer‐associated fibroblasts secrete IL‐6, which serves as the principal upstream molecule responsible for triggering tumorous Osteopontin." (PMID 38946720, 2024). "Concentrations of the immunosuppressive cytokine TGFβ and the immunostimulatory cytokine IL-6 are increased in advanced stages of cancer and are strongly associated with poor prognosis in cancer patients." (PMID 37511415, 2023). "Various observational studies have proposed that circulating IL-6 can describe inter-individual variability in cancer predisposition." (PMID 38024543, 2023). "mRNA encoding for IL6, a cytokine playing an essential role in the survival of cancer cells with chromosomal instability, via the cGAS/STING pathway, was also robustly increased." (PMID 37108510, 2023). "A higher concentration of Il-6 stimulated by activin A can cause transformation of cancer cells to distant metastases." (PMID 37373969, 2023). "During the course of cancer therapy, a high change rate of IL‐6, IL‐8, CXCL10, CCR1, and CCL5 was significantly associated with poor PFS." (PMID 37062076, 2023). "Cancer-associated fibroblast (CAF) sub-clusters showing high expression of IL6, CCL2, S100A4, PDPN, and FGF7 were identified in both primary and metastatic samples." (PMID 38328306, 2023). "In the Cancer Hallmark pathway analysis, IFNα, IFNγ, inflammatory responses, and IL6/JAK/STAT3 signaling were suppressed significantly by JGT in tamoxifen-treated GH rats." (PMID 36980301, 2023). "After treatment, the upregulation of serum inflammatory markers C-reactive protein (CRP) and interleukin-6 (IL-6) predicts a high risk of cancer recurrence and patient death." (PMID 36835173, 2023). "It has also been shown that cancer cells can hijack adipocytes and transform them into cancer-associated adipocytes (CAAs), that overexpress IL-6 and other pro-tumor cytokines." (PMID 37182144, 2023). "Interleukin-6 (IL-6) is considered to be an inflammatory cytokine that plays a vital role in inflammation-associated cancers." (PMID 37007111, 2023). "In agreement with the previous data, IL-6 strongly promoted cancer cell migration, causing the complete closure of the wound after 72 h." (PMID 36675246, 2023). "An evaluation of the levels of several proteins associated with inflammation: IL-6, D-dimer and C-reactive protein enabled the association of high levels of IL-6 with a 40% increase in cancer risk." (PMID 37491285, 2023). "Meanwhile, the IL-6/JAK/ STAT3 Signaling pathway is overactivated in many forms of cancer, and it is implicated in driving cancer cell proliferation, invasion, and metastasis, as well as interacting with TIME to inhibit antitumor immune responses." (PMID 36949898, 2023). "Pathway analysis showed that PANoptosis score was positively correlated with pathways linked to immune and inflammatory responses in pan-cancer, such as IL6-JAK-STAT3 signaling, the interferon-gamma response, and IL2-STAT5 signaling." (PMID 36890219, 2023). "Nevertheless, earlier studies on the relationships of polymorphisms in IL-6 promoter through predisposition to various cancers are rather contrary." (PMID 38024543, 2023). "For example, contrary to normal fibroblasts, cancer associated fibroblasts (CAFs) release high levels of IL-6 and CCL2 upon STAT3 activation in co-cultured breast cancer cells,promoting the stem cell renewal and atmosphere forming capacity." (PMID 37720284, 2023). "In a quantitative review from 2007, a positive association between cancer-related fatigue and circulating levels of interleukin-6 (IL-6), interleukin-1ra and neopterin was found." (PMID 37936126, 2023). "Interleukin (IL)-6 is a pleiotropic cytokine that is both an inflammatory cytokine and a cancer-associated cytokine." (PMID 37817809, 2023). "They found that, following treatment with increasing doses of tocilizumab, only cancer cell lines expressing high levels of IL-6 and/or IL-6R were susceptible to tocilizumab-induced cell death." (PMID 36717545, 2023).